IL1B (interleukin 1 beta)
Diseases named in the same sentence as IL1B in open-access papers (continued):
Sharing a sentence is not in itself a finding about the gene and the disease.
infection (continued). "The early phases of infection show a systemic decrease in pro-inflammatory cytokines (IL-1β, IL-6, and TNFα), accompanied by an increase in the anti-inflammatory cytokine IL-10." (PMID 39340101, 2024). "The exacerbated infection in Tercko/ko mice correlates with heightened inflammation, manifested by elevated interleukin-1β (IL-1β) levels and activation of the NLR family pyrin domain containing 3 (NLRP3) inflammasome within the lung." (PMID 39607755, 2024). "TNF-α promotes the production of other proinflammatory cytokines, such as IL-1β and IL-6, and induces the expression of adhesion molecules and chemokines, which attract immune cells to the site of injury or infection." (PMID 38397895, 2024). "Considerable inflammatory cells infiltrating in the endometrium, with high levels of pro-inflammatory cytokines of interleukin (IL)-6, IL-1β and tumor necrosis factor-α mRNA after infection." (PMID 39545261, 2024). "The TNF-α and IL-1β cytokines in teleost fish are powerful pro-inflammatory cytokines released by several immune cells during infection or tissue damage." (PMID 39243089, 2024). "Infection of BRB with ZIKV leads to the generation of IL-1β, IL-6, IFN-α, IFN-β, TNF-α, CCL5 and CXCL-10." (PMID 39795906, 2024). "EVs from Ascaris-exposed hMDMs thereby seem to lower the infection-driven IL-1β to an optimal range suitable for Mtb growth control." (PMID 39569198, 2024). "This literature indicated that IL-1β and IL-6 are mediating host protection against parasites infection, activating and inflammatory responses." (PMID 39749330, 2024). "At the site of infection, IL-1β and IL-17 trigger the recruitment of immune cells and microbial responses (such as ROS and NO production) that are detrimental to the Leishmania parasite." (PMID 38190401, 2024). "Serum PTX3 has been identified as a potential predictor of mortality during infection and is known to be associated with TNF-α and IL-1β, which are crucial proinflammatory mediators." (PMID 39666228, 2024). "Given the significance of IL-1β, our blocked experiments have confirmed its pivotal role as the primary stimulus for macrophage ferroptosis in the initial stages of infection." (PMID 39353913, 2024). "IL-1β is one of the most powerful proinflammatory cytokines against infection and regulates the expression of several molecules involved in inflammation." (PMID 38256071, 2024). "It has been demonstrated that C. faecalis regulates the production of the cytokines IL-1β and IL-6, thereby coordinating the inflammatory response during infection." (PMID 38671184, 2024). "The inflammatory biomarker profile in the liver of infected rabbits was characterized by a decrease in IL-1β expression at very similar levels after infection with both genotypes (3.6-fold reduction and 3.1-fold reduction for GI.1 and GI.2, respectively)." (PMID 39273479, 2024). "On the contrary, we found that the ECRG4 KO mouse infection had increased expression of IL1β (P = 0.0053), IL-6 (P = 0.047) and TNFα (P = 0.024), with a trend towards increased CXCL1." (PMID 39509414, 2024). "Subsequently, M1 macrophages produce tumor necrosis factor-alpha (TNF-a), interleukin-1 beta (IL-1β), and reactive oxygen species (ROS) to combat infection, clear foreign substances, and ultimately repair the damage." (PMID 39199705, 2024). "Following the infection of macrophages and nanomaterial co-cultures by C. albicans, we evaluated IL-1β, IL-6 and TNF-α transcription levels using RT-qPCR." (PMID 39407477, 2024). "Beyond G-CSF, infections also induce the expression of a wide array of inflammatory cytokines by myeloid cells including IL-1α and IL-1β, interferons, tumor necrosis factor (TNF), and IL-6, the roles of which on bone have been recently reviewed [19•]." (PMID 38198032, 2024). "IL-1β production is also required for strong and sustained neutrophil recruitment to the site of infection by Leishmania." (PMID 39221251, 2024).
infection (continued). "Of interest, IFN-γ, IL-1β and IL-6 lung cytokine levels were significantly increased in the lung at both two- and three-weeks post-infection." (PMID 38198478, 2024). "High levels of TNF-α, IL-1β and IL-6 and MDA in the SE-stimulated mice indicated that SE infection caused an imbalance in the redox status, resulting in oxidative stress and inflammatory responses." (PMID 39456517, 2024). "This process results in the cleavage of pro-IL-1β into its active form, promoting the recruitment of immune cells to the infection site and driving inflammation." (PMID 39770727, 2024). "Infection with N. gonorrhoeae produced a significant early6h response of IL-1β, TNF-α, and MIP-1β (CCL4)." (PMID 38704381, 2024). "M. bovis SB1564 (0.268 pg/mL) and M. bovis SB0120 (0.203 pg/mL) had a slight increase in IL-1β production one day and two days post-infection, respectively." (PMID 38399810, 2024). "This is compatible with the outputs of the experiments with BODIPY FL vancomycin and suggests that a minimal concentration of meropenem is required to induce alterations in the IL-1β secretion levels when the carbapenem is applied post-infection." (PMID 38411952, 2024). "The results showed that on both days 3 and 5, the 10 mg/kg or 100 mg/kg probenecid-treated mice had significantly (p < 0.05) reduced IL-6, TNF-α, and IL-1β when compared to the infection control mice." (PMID 38275962, 2024). "S. aureus exposure did not increase the capacity of macrophages to directly kill intracellular E. coli but instead promoted IL-6, TNF, and IL-1β production by these cells, leading to enhanced recruitment of neutrophils to clear the infection." (PMID 39618498, 2024). "We additionally report a synergistic increase in IL-1β expression after infection with the co-culture of P. gingivalis and F. nucleatum." (PMID 38612423, 2024). "The expression of IDO1 and IL-1β in the infected cells was stronger with all virulent M. tuberculosis strains, compared to infections with the avirulent strain." (PMID 39597535, 2024). "Infection or CNS damage can activate microglia, and activated microglia release IL-6, IL-1β, and TNF-α." (PMID 39661619, 2024). "We observed significant increases in TNF-α, IL-1β, and IL-8 expressions and a clear synergistic increase in IL-6 expression with the P. gingivalis and F. nucleatum co-culture infection." (PMID 38612423, 2024). "Strikingly, by blocking IL-1β, total infection in the epidermis decreased by 33% and in the dermis by 65%." (PMID 38793609, 2024). "The invasive pathogen Shigella flexneri (S. flexneri) is accompanied by the release of inflammatory cytokines IL-1β and IL-18 during the infection stage." (PMID 38019021, 2024). "The increased plasma IL-1β and IL-8 found in this study have also been reported in a larger LongC cohort with a mean post-infection time of 140 days." (PMID 38534322, 2024). "Nevertheless, we observed that PCC patients who were vaccinated post-infection less frequently reported gastrointestinal symptoms and had lower levels of IL-1β and IL-18." (PMID 38316833, 2024). "On day 2 post infection, Il1a and Il1b expression were significantly higher compared to either LPS only or RSV only mice." (PMID 39127259, 2024). "IL-1β is a proinflammatory cytokine primarily produced by activated macrophages and monocytes in response to infection, injury, or stress." (PMID 38397895, 2024). "We found that levels of IL-6 at 24 hours after infection was significantly lower in the lungs of mice treated with CETPi compared with control, whereas levels of IL-1β and TNF-α were unchanged." (PMID 38646937, 2024). "Patients in the death group presented higher levels of IL-4 and IL-1β at all timepoints evaluated, maintaining constant elevated levels throughout the course of infection." (PMID 39408907, 2024). "Live NTHi was used to mimic an actual infection and their inhibitory activities against the production of IL-1β, a pivotal mediator in COPD, were evaluated." (PMID 38406294, 2024).
infection (continued). "As a crucial component of the innate immune system, inflammasomes are activated by cellular infection or stress, which leads to the secretion of proinflammatory cytokines IL-1β and IL-18." (PMID 38891697, 2024). "Again, infection with M84stop significantly increased IL-1β-luciferase release compared to WT MCMV infection." (PMID 38278864, 2024). "The variability in the literature concerning IFN-γ underscores the significance of our study, which assessed IFN-γ at multiple infection stages and examined the dynamic release patterns of IL-4, IL-1β, and IL-6." (PMID 39408907, 2024). "We demonstrated that positive infection-associated urinary biomarkers NGAL, IL-8, and IL-1β, in symptomatic subjects with positive SUC and/or M-PCR results was associated with definitive UTI cases." (PMID 38297221, 2024). "Skin damage and vector-derived factors egested during the infectious blood meal induce a rapid and intense neutrophil recruitment to the site of infection, characterized by chemokine and cytokine release and upregulation of IL-1β." (PMID 39250503, 2024). "IL-1β regulates spermatogenesis and IL-6 is cytokines produced in response to infection and tissue damage." (PMID 38629098, 2024). "IBV DMV/1639 infection led to notable upregulation of IL-1β and IL-6 mRNA expressions at various early time points, diverging from IBV Conn A5968-infected TOCs and non-infected controls." (PMID 39472003, 2024). "Ultimately, we posit that ferroptosis acts as a crucial initiating factor in the host response to GBS infection, with IL-1β playing a significant role in the resistance to infection by serving as a key inducer of ferroptosis." (PMID 39353913, 2024). "Our previous study reported that the pro-inflammatory factors IL-1β and IL-6 secreted by macrophages were markedly reduced following the coaggregated S. gordonii and Fnp infection." (PMID 38761182, 2024). "Consistently, our study showed the elevated IL-1β in the placentas of Trem2-/- mice compared to wildtype mice following infection." (PMID 39250507, 2024). "Neutrophils also released mature IL-1β in response to infection by all strains, albeit to a lesser extent than after LPS plus nigericin stimulation." (PMID 38803236, 2024). "Following infection with M. tb, NF-κB is activated and translocates to the nucleus, where it stimulates the expression of a range of proinflammatory cytokines, such as IL-1β, IL-6, and TNF-α." (PMID 38920649, 2024). "At 10 days post infection, the expression of IL-1β (p = 0.005), IL-8 (p = 0.0002), IL-12 (p = 0.0003), and IFNγ (p = 0.006) was also significantly affected." (PMID 38790647, 2024). "Although proinflammatory cytokines such as IFN‐γ and IL‐1β are thought to be the major mediators of neuroinflammation, their role in brain injury and infection remains disease‐defined." (PMID 39116324, 2024). "IL-1β, a crucial pro-inflammatory cytokine in response to infection, impacts nearly all types of cells." (PMID 38255822, 2024). "The expression of the proinflammatory marker genes il1b and mmp9 is strongly induced in zebrafish larvae shortly after infection with M. marinum." (PMID 39336115, 2024). "CXCL8, also called IL-8, is a chemotactic factor involved in the inflammatory response by attracting neutrophils, basophils, and T cells to eliminate pathogens and protect the host from infection, whereas IL1B is a potent proinflammatory cytokine." (PMID 38920854, 2024). "The gene expression levels of four cytokines; TNF-α, IL-6, IL-1β, and IL-8 were tested in the cell lines after infection." (PMID 39427065, 2024). "In the case of spleen samples, macerates from the Mtb single-infection group were found to have significantly higher concentrations of IL-1β, G-CSF and MIP-1β than the HIV single-infection group." (PMID 38799434, 2024). "The research discussed here indicates that T. gondii products are able to activate the NLRP3 inflammasome, which then produces IL-1β to control the infection." (PMID 38623843, 2024).
infection (continued). "Despite the rapid clearance, A. baumannii infection resulted in neutrophil and inflammatory monocyte recruitment into the lungs and increased expression of the pro-inflammatory cytokines Il1a, Il1b and Tnfa at 12 h post infection." (PMID 39127259, 2024). "Since NLRP3-dependent pyroptosis is executed by GSDMD, we also depleted GSDMD to verify its role in RVFV-infection induced IL-1β release." (PMID 39213434, 2024). "This receptor controls the expression of inflammatory markers, such as NLRP3 and IL-1β, which helped control parasitic replication during infection with the EGS strain." (PMID 39267751, 2024). "Compared with WT infection, deletion of yfiD led to the superior transcription of IL-1α (NP_034684.2), IL-1β (NP_032387), and IL-6 (NP_112445.1)." (PMID 38332126, 2024). "Pro-inflammatory cytokines such as TNF-α and IL-1β play crucial roles in immune responses, serving as vital mediators that communicate tissue distress due to infection or injury." (PMID 39452085, 2024). "The mRNA expression of IL-6 in colon tissue was significantly increased due to infection and the mRNA of IL-1b also tended to increase." (PMID 39081865, 2024). "Upregulation of IL-1β and IL-6 mRNA expression was described in the cecum and ileum of broilers after in vivo infection with C. jejuni." (PMID 38907359, 2024). "IL1-β is a pro-inflammatory cytokine and plays a role in the immune response to infections and injury, while TNF-α, also pro-inflammatory, is involved in inflammation and cell death." (PMID 38600563, 2024). "For IL-1β, a PCLS age-effect was additionally detected within PAO1 infection, indicating that an increased amount of IL-1β is produced by infected PCLS from old compared with young mice after 4 h." (PMID 38178102, 2024). "As a response to the infection, proinflammatory cytokines are released and several studies suggest that TNFα, IL-1β, and IL-6 are significantly increased during infections and can cause learning and memory impairments." (PMID 39772122, 2024). "DENV can facilitate the assembly of NLRP3 inflammasome during infection, which then regulates the cleavage of inactive pro-IL-1β (interleukin 1 beta, IL1B) via activating Caspase-1 (CASP1), a process that yields mature IL1B, thereby activating inflammation." (PMID 38355571, 2024). "MNKs have been implicated in mediating the production of pro-inflammatory cytokines, such as TNF-α, IL-6, and IL-1β, during infection and inflammation." (PMID 38980024, 2024). "M1 macrophages can control infection by releasing a wide spectrum of factors including IL-1β, TNF-α, IL-6, and iNOS expression." (PMID 37227688, 2024). "Pro-inflammatory cytokines play a key role in the host immune response to infection and they include IL-1β, IL-8, IL-12, IL-17, IFN-γ, and TNF-α." (PMID 38543749, 2024). "In the early stages of infection, IL-1β produced by macrophages binds IL-1R on airway epithelial cells and stimulates them to produce neutrophil-recruiting chemokines such as CXCL8, a cascade which can be amplified with chronic infection." (PMID 39015565, 2024). "After infection with the L. europaeus/GI.2 genotype, IL-1β expression in the lungs increased by 6.7-fold, and 3.1-fold changes for GI." (PMID 39273479, 2024). "A comparison of the IL-1β mRNA levels between the day 20 and day 30 post-infection groups revealed a statistically significant decrease in the IL-1β mRNA levels at day 30 post-infection (p < 0.05), which constituted another noteworthy finding." (PMID 39766497, 2024). "A statistically significant reduction in IL-1β levels in culture supernatants was seen 24 hours post-infection with AN_CH_37, as well as other pro-inflammatory cytokines, namely IL-6 and TNF-α." (PMID 38590438, 2024). "Later in infection, IL-1β signaling also triggers the activation of IL-17A secreting T helper 17 (Th17) cells, modulating the Th17/T regulatory cell (Treg) balance, which will be discussed in greater detail below." (PMID 39015565, 2024).
infection (continued). "The levels of pro-inflammatory cytokines such as IL-1α, IL-1β, IL-2, IL-6, IL-12, IL-17, INFγ, and TNFα increased in the serum of mice infected with fungal strains from a very early stage (3 h) to 7 days post infection." (PMID 38783167, 2024). "Infection-induced IL-1β activation contributes to the impaired endothelial barrier function and procoagulant/anti-fibrinolytic shift in the endothelium." (PMID 39281671, 2024). "Analysis of lung destruction showed that H37Rv infection in mice severely damaged the lung as analyzed by IL-1β immunostaining." (PMID 39548211, 2024). "In the current study, we treated BC 5,637 cells with LPS to mimic the inflammatory microenvironment caused by infection and found that LPS notably increased the levels of NLRP3 and inflammatory cytokines, including IL-1β, IL-18, and TNF-α." (PMID 39144184, 2024). "Throughout the infection, we noted that pro-inflammatory factors such as IL-1β and TNF-α consistently increased in both serum and liver tissue, while anti-inflammatory factors like IL-4 and IL-10 showed a continuous decline." (PMID 39749332, 2024). "In parallel, infection of TOCs with IBV DMV/1639 resulted in a marked increase in IL1-β mRNA expression at 3, 6, and 12 hpi (P < 0.05) and IL-6 mRNA expression at 3 and 6 hpi (P < 0.05) compared with both IBV Conn A5968-infected TOCs and non-infected controls." (PMID 39472003, 2024). "IL-1β is released during infection, inflammation, and cell injury by monocytes and macrophages and by nonimmune cells as well." (PMID 38960876, 2024). "As expected, gnotobiotic chicks with S. Typhimurium infection showed multiple fold increase in the expression levels of various pro-inflammatory cytokines and chemokines; IL-18, IL-1β, IL-6, and IL-8L1 at day 5 post-infection." (PMID 38315031, 2024). "Activated neutrophils release pro-inflammatory cytokines, such as TNF-α, IL-1β, and IL-6, exacerbating inflammation instead of providing protection as observed in infection and tissue injury scenarios." (PMID 38794163, 2024). "A detailed temporal analysis of the pro-inflammatory cytokines secreted by human PBMCs showed an increased concentration of IL-1β, IL-6 and TNFα starting at 4 h post-infection, with IFNγ amounts rising at 8 h post-infection." (PMID 38793740, 2024). "IL1B (interleukin-1 beta) indicates an inflammatory response, and high expression after an infection-simulating treatment is expected." (PMID 38721267, 2024). "In Zbp1+/+ BMDMs, the IL-1β level was significantly higher upon infection with ΔVP22 or ΔVP22 (51–246 aa) than with viruses containing an intact N-terminal 1–50 aa VP22 domain." (PMID 39475237, 2024). "Mice were injected intraperitoneally with anti-IL-1α, anti-IL-1β, or control antibody on days −1, 1, 3, and 5 of infection." (PMID 38382577, 2024). "IL-1α and IL-1β are pro-inflammatory and are produced during infection, tissue damage, or other inflammatory stimuli such as exposure to allergens, toxins, or stress." (PMID 38251210, 2024). "The real-time quantitative PCR analysis demonstrated that the IL-1β mRNA expression levels showed an upward trend 8 h after the infection of the IPEC-J2 cells with PEDV and reached a peak at 24 h." (PMID 39728983, 2024). "NOD-like receptor protein 3 (NLRP3) inflammasome is a molecular platform that triggers caspase-1 and facilitates the secretion of interleukin (IL)-1β and IL-18 in response to cellular infection or stress." (PMID 38681198, 2024). "We then analyzed intracellular mature IL-1β production in the lungs ex vivo by flow cytometry 3 wk after H37Rv infection." (PMID 38803236, 2024). "Previous studies have shown that RNA viruses can induce mature IL-1β secretion by activating the NLRP3 inflammasome pathway at different stages of infection." (PMID 39728983, 2024).